H3P2 (H3 histone pseudogene 2)
Synonyms: p03
Gene: Processed pseudogene on chromosome 1 (52,943,536 to 52,943,930, reverse strand). Ensembl gene ENSG00000237279.
Diseases named in the same sentence as H3P2 in open-access papers:
H3P2 is named in the same sentence as 5 diseases in open-access papers, as found by Europe PMC text mining. Sharing a sentence is not in itself a finding about the gene and the disease.
H3P2 shares sentences with these, for which no sentence is quoted: tumor (2 papers); brain tumor (1); glomerulonephritis (1); lung carcinoma (1); lupus (1).